TAF6L (TATA-box binding protein associated factor 6 like)
Description:
Functions as a component of the PCAF complex. The PCAF complex is capable of efficiently acetylating histones in a nucleosomal context. The PCAF complex could be considered as the human version of the yeast SAGA complex (Probable). With TAF5L, acts as an epigenetic regulator essential for somatic reprogramming. Regulates target genes through H3K9ac deposition and MYC recruitment which trigger MYC regulatory network to orchestrate gene expression programs to control embryonic stem cell state. Functions with MYC to activate target gene expression through RNA polymerase II pause release (By similarity).
Synonyms: PAF65A
Tractability: PROTAC: ubiquitination databases record sites on it.
Gene: Protein-coding gene on chromosome 11 (62,771,307 to 62,787,342, forward strand). Ensembl gene ENSG00000162227.
Subcellular location: Nucleus
Subcellular location (Human Protein Atlas): Nucleoplasm
Pathways (Reactome):
Chromatin organization: HATs acetylate histones
Gene Ontology:
Molecular function: protein binding; transcription coactivator activity; DNA binding; protein heterodimerization activity; RNA polymerase II general transcription initiation factor activity
Biological process: chromatin remodeling; positive regulation of DNA-templated transcription; regulation of DNA repair; regulation of DNA-templated transcription; regulation of RNA splicing; regulation of somatic stem cell population maintenance; regulation of transcription by RNA polymerase II; RNA polymerase II preinitiation complex assembly; transcription initiation at RNA polymerase II promoter
Cellular component: extracellular exosome; nucleoplasm; nucleus; SAGA complex; histone deacetylase complex; SLIK (SAGA-like) complex; transcription factor TFIID complex
Genetic constraint (gnomAD): Loss-of-function variants: 35 observed, 58.04 expected, observed/expected ratio (o/e) 0.6, 90% interval 0.46 to 0.8. The upper end of that interval is the gene's LOEUF score, 0.8, which puts it in group 3 of 6, group 1 being the genes least tolerant of losing a copy. Missense variants: 782 observed, 821.02 expected, observed/expected ratio (o/e) 0.95, 90% interval 0.9 to 1.01. Synonymous variants: 417 observed, 365.79 expected, observed/expected ratio (o/e) 1.14, 90% interval 1.05 to 1.24.
Homologues: Orthologues: macaque TAF6L (99% identical), dog TAF6L (94% identical), mouse Taf6l (93% identical), rat Taf6l (93% identical), chimpanzee TAF6L (88% identical), guinea pig TAF6L (85% identical), pig TAF6L (85% identical), rabbit TAF6L (84% identical), zebrafish taf6l (67% identical), tropical clawed frog taf6l (60% identical), Caenorhabditis elegans taf-6.2 (21% identical), Drosophila melanogaster mia (17% identical), and 1 more. Paralogues in human: TAF6 (24% identical).
Diseases named in the same sentence as TAF6L in open-access papers:
TAF6L is named in the same sentence as 3 diseases in open-access papers, as found by Europe PMC text mining. Sharing a sentence is not in itself a finding about the gene and the disease. The quoted sentences say what the papers report.
cancer (1 paper, 2025). A tumor composed of atypical neoplastic, often pleomorphic cells that invade other tissues. "Specifically, the elucidated interplay between KLF6, TAF6L and FOSL2, along with their regulatory influences on SEMA3C and the Wnt-β-catenin pathway, enhancing our understanding of the complex networks underlying cancer drug resistance." (PMID 40082673, 2025).
TAF6L also shares sentences with these, for which no sentence is quoted: glioma (2 papers); Sepsis (1).